IL10 (interleukin 10)
Diseases named in the same sentence as IL10 in open-access papers (continued):
Sharing a sentence is not in itself a finding about the gene and the disease.
tumor (continued). "Specifically, tumor-associated macrophages (TAMs) and cancer-associated fibroblasts (CAFs) induce the upregulation of regulatory T cells (Tregs) through the release of interleukin-10 (IL-10), transforming growth factor-beta (TGF-β), and C-C motif chemokine ligand 22 (CCL22)." (PMID 39200233, 2024). "Furthermore, interleukin-10 secreted by tumor-associated macrophages (TAMs) also activate regulatory T cells." (PMID 39136031, 2024). "Moreover, a significant production of cytokines TNF-α and IL-10 was noticed in the Cutibacterium-treated cells, further indicating a close association of this bacterium with tumor activities." (PMID 39201629, 2024). "During the tumor development phase, tumor-associated macrophages secrete anti-inflammatory factors, including IL-10, which stimulates polarization of naive T cells into T regulatory cells, and TGF-β1, which is the main cytokine that induces anergy of T cytotoxic and natural killer cells." (PMID 38455363, 2024). "In addition, overexpression of YAP1 induces the polarization of macrophages into the M2 phenotypes (tumor-associated macrophages) by regulating different genes such as iNOS, MerTK, IL-10, STAT3, CD163, CD206, Arg-1, CD86, and TNF-α in the naive macrophages." (PMID 39630608, 2024). "Classical activation of Mφ, which is associated with high IL-12 and low IL-10, by bacterial products may offset the protumor effects of tumor-associated Mφ, which has low IL-12 and elevated IL-10." (PMID 38962577, 2024). "Of note, IL‐10 in high‐risk HPV infection is associated with tumor formation and progression." (PMID 37681284, 2024). "Several biomarkers have been investigated in PCNSL, including cytokine IL-10, which is overexpressed in tumor tissue and detected in the CSF of patients and is associated with the immunosuppressive microenvironment of the tumor, potentially serving as a diagnostic and prognostic biomarker." (PMID 39144147, 2024). "Nonetheless, individuals in whom proper IL-10 signaling is compromised, whether mice or humans, display a markedly heightened susceptibility to spontaneous tumor development." (PMID 39204319, 2024). "Immunosuppressive cell types like myeloid-derived suppressor cells (MDSCs), tumor-associated macrophages (TAMs), and regulatory T cells (Tregs) produce anti-inflammatory cytokines, such as interleukin-10 (IL10), IL4, transforming growth factor-beta (TGF-β) that inhibit the CAR T function." (PMID 38962014, 2024). "Besides IL-10, various cytokines have been implicated in suppressing anti-tumor immunity, including transforming growth factor-β (TGF-β) and interleukin-35 (IL-35)." (PMID 38629061, 2024). "In addition to tumor cells, myeloid-derived suppressor cells (MDSCs), tumor-associated macrophages (TAMs), and regulatory T cells (Tregs) also have the ability to inhibit natural killers by producing molecules such as Il-10, TGF-β, ADO, and IDO." (PMID 39769334, 2024). "Tumor-associated macrophages (TAMs) are another source of IL-10 in MA." (PMID 38279997, 2024). "Moreover, elevated levels of IL-10 were associated with a higher risk of all-cause mortality in cases with ER+PR+ tumours (HR1-SD 1.35, 95% CI 1.10–1.65)." (PMID 39342063, 2024). "In this context, we and others have demonstrated that the delivery of a TLR3 agonist into the bronchoalveolar space reduces the presence of M2-associated arginase- and IL-10-positive AMs in tumor-bearing lungs, possibly through an IFN-αβ dependent mechanism, as suggested." (PMID 38776331, 2024). "In the context of OSCC, some reports have demonstrated that several cytokines, particularly TNF-α, promote tumor progression by upregulating the genes associated with neutrophil recruitment and invasion, as well as IL-10, which has been associated with a more aggressive OSCC phenotype." (PMID 39204206, 2024).
tumor (continued). "The convergence of these two pathways activates signals such as NF-kβ and hypoxia-inducible factor (HIF-1α) with STAT3 in tumor cells, which causes monocyte recruitment and the production of pro-inflammatory signals such as IL-10 or TGF-β in the TME via M2-like TAMs." (PMID 38672714, 2024). "Additionally, MSCs stimulate tumor‐associated neutrophils to adopt an anti‐inflammatory phenotype and release IL‐10 and prostaglandin E2 (PGE2), suggesting their role in regulating neutrophil activity." (PMID 39070181, 2024). "Furthermore, tumor-associated macrophages (TAMs) derived IL-10 attenuated T-cell anti-tumor immunity in lung cancer mice model, which was correlated with increased expression of B7-H3 on the membrane." (PMID 37605389, 2024). "It is possible that IL-10 may also be associated with reducing the anti-tumor function of NK cells by inducing CISH expression." (PMID 36830840, 2023). "PMs can be switched to tumor-associated macrophages (TAMs) in ascites with pro-tumor effect by releasing various soluble mediators, including IL-6, IL-10, CCL18, CCL22, TNF-α, TGF-β, and EGF that triggers pro-tumorigenic signaling pathways in tumor cells and infiltrating leukocytes in the TME." (PMID 37932814, 2023). "Nevertheless, further investigation is imperative in order to comprehend the underlying processes of IL-10 whether it is a tumor-stimulating or inhibitory factor." (PMID 38075864, 2023). "In vivo, IL-10, M-CSF, and TGFβ are all involved in the polarization and accumulation at the tumor site of tumor-associated macrophages (TAMs), which display features of alternatively activated M2 macrophages and contribute to the suppression of anti-cancer T-cell-mediated immune responses." (PMID 37345186, 2023). "Furthermore, network analysis links these key TF modules to open chromatin regions in genes associated with M2 polarization, tumor growth, and metastasis, including IL-10, TIMP1, and EREG." (PMID 37365178, 2023). "Furthermore, Bregs, releasing IL-10, induce the differentiation of tumor-associated macrophages (TAMs), skewed toward a M2 macrophage phenotype, that inhibits effector T and NK cells." (PMID 37046842, 2023). "Some cytokines, such as IL-8 and IL-10, may counteract the efficacy of PD-L1/PD-1 blockade therapy and affect the expression of PD-L1 on the surface of tumor-associated macrophages (TAM), the most abundant immune cells in the tumor microenvironment (TME)." (PMID 37603071, 2023). "We also observed that IL-10 deficiency suppressed the migration capacity of tumor cells and promoted tumor cell apoptosis, indicating that tumor cells with impaired migration, and viability contribute to pleural stomata occlusion and lymph vessel obstruction to a lesser extent." (PMID 37533789, 2023). "In particular, tumour-associated macrophages (TAMs), such as M2 macrophages, promote tumour growth through angiogenesis, which is enhanced when Th2-associated cytokines such as IL-4 and IL-10 are upregulated." (PMID 36612301, 2023). "Furthermore, activated STAT3, which is associated with a poor prognosis in cancer, participates in tumor progression via IL-10 and IL-6, and tightly regulates M2 polarization and activation status." (PMID 37759870, 2023). "Studies have shown that MDSCs recruited to the tumor microenvironment mature into tumor-associated macrophages that lose expression of Ly6C, gain expression of F4/80 and Cx3Cr1, and maintain expression of IL-10 and PD-L1." (PMID 38094302, 2023). "IL-10 is immunosuppressive and associated with tumor progression." (PMID 37373957, 2023). "In macrophages, GS activity driven by IL10 is associated with a pro-tumor M2-like phenotype." (PMID 37781517, 2023). "Furthermore, patients with various tumors have been found to have elevated circulating concentrations of IL-10, which is known to be associated with tumor progression and metastasis." (PMID 37762285, 2023).
tumor (continued). "Furthermore, IL-10 produced by M2-polarized tumor-associated macrophages was related with EMT in pancreatic cancer." (PMID 37779872, 2023). "Additionally, in terms of immunosuppression, tumor-associated MSCs can encourage tumor cells to escape from immune cells by releasing IL-10 to downregulate MHC-I expression on tumor cells." (PMID 37055849, 2023). "Tumor-associated macrophages are known to suppress adaptive immunity through secretion of variety of chemokines and cytokines such as tumor necrosis factor-α, interleukin (IL)-1, IL-6, and IL-10 to promote tumor growth, angiogenesis, invasion, and migration." (PMID 37408277, 2023). "Tumor-associated macrophages (TAMs) typically exhibit an M2-like phenotype which can secrete various immune suppress factors, including IL-10, TGFβ, and proangiogenic factors, and previous research has established a link between TAMs and disease progression and poor prognosis of NSCLC patients." (PMID 36389757, 2022). "IL-10+ PB infiltration was associated with an upregulation of the T cell exhaustion marker Tim-3 and higher tumor size and stage, suggesting that they may suppress T cell immunity." (PMID 36230721, 2022). "Thirdly, the weak immunogenicity of IL-10, and the confinement and decorative effect of tumor antigens, together causes immune escape phenomenon due to the inability of the organism to recognize tumor antigens." (PMID 36567775, 2022). "Tumor-associated B cells can promote tumor inflammation, for instance through B cell receptor stimulation by melanoma derived antigens, and also inhibit T cell-dependent therapy responses through the release of IL-10 and TGF-β." (PMID 36175961, 2022). "Moreover, both IgG4 and tumor IL-10 are associated with shorter recurrence-free survival (RFS) and overall survival (OS)." (PMID 35681689, 2022). "In AOM-induced interleukin (IL)-10-deficient mice, curcumin administration resulted in increased numbers of Lactobacilli colonies and microbiota richness, with subsequently alleviated tumor burden, suggesting a correlation between the microbiota and reduced tumor burden." (PMID 36557939, 2022). "Interestingly, the GC group had a significantly higher amount of IL-10 mRNA, which is probably released by tumor-associated macrophages (TAMs) and creates an immune evasive microenvironment and dictates poor prognosis." (PMID 35572666, 2022). "Generally, M1-polarized macrophages exert anti-tumor effects through eliminating and destroying phagocytosed tumor cells, while M2-like macrophages, activated by IL-4, IL-10 and IL-13, resemble tumor-associated macrophages (TAMs), which promote tumor progression though immunosuppressive functions." (PMID 35807802, 2022). "IL-10 is secreted by tumor-associated macrophages TAMs and Treg cells in GC." (PMID 35884907, 2022). "Tumor-associated macrophages (TAMs) are the predominant immune cell types with immunosuppressive M2 polarized phenotypes that secrete tumor cytokines (IL-4, IL-10, and IL-13)." (PMID 36479071, 2022). "In addition, the presence of IgA+ plasma cells expressing PD-L1 and IL-10 in the tumor environment was associated with poor T-cell immunity in human liver cancers." (PMID 35965506, 2022). "Treg cells promote immunosuppression by inhibiting immune response to cancer cells, and the expression of CD4+ CD25+ CD127low Tregs had a positive correlation with TGF-β1 and IL-10 expressions and was closely linked to tumor occurrence and development and immunotherapy reactivity." (PMID 35820903, 2022). "Tumor associated macrophage (TAMs) are classically known to promote tumor growth and metastasis, but following treatment with IL-12, TAMs exhibit reduced production of tumor promoting factors (IL-10, MCP-1, MIF, and TGFβ)." (PMID 35634303, 2022). "The STAT3-dependent tumor-associates factors such as IL-10, VEGF and basic fibroblast growth factor (bFGF) could strengthen the immunosuppressive network and promote tumor vasculariztion that hinders IFN-γ-dependent effect of CD8+ T cells." (PMID 34875483, 2022).
tumor (continued). "The early soluble factors may then help shape later tumour associated factors such as IL-10, neutrophils, PD-L1-expressing myeloid cells and Ly6G-Ly6Cintermediate monocytes, which play roles in tumour development." (PMID 35226704, 2022). "Moreover, these fucosylated glycans can serve as ligands for DC-SIGN positive tumour-associated macrophages, modulating their activation and inducing the production of IL-10." (PMID 35017635, 2022). "G-MDSC could be differentiated into tumor-associated neutrophils, which immunosuppressive functions are mediated by metabolites (e.g. Arg-1, ROS, NO) and soluble regulatory factors IL-10, MMP-9, and VEGF7–9." (PMID 35589776, 2022). "Additional correlation analyses showed that IL7R expression was significantly associated with markers of cells involved in immunosuppression such as CD68, CD163, MRC1, and IL10 (tumor‐associated macrophages), CD4, FOXP3 (regulator T lymphocytes) and CD274 (PD‐L1)." (PMID 36054746, 2022). "Furthermore, IL-10 deficiency reduced the Tregs-mediated immunosuppression through reduction of the expression of neuropilin on Tregs, leading to the tumor regression and enhancing the anti-tumor immunity." (PMID 35585567, 2022). "A possible association between IL-10 mRNA and the tumor grade has been demonstrated." (PMID 35054779, 2022). "In addition, by producing angiogenic factors, for example, vascular endothelial growth factor (VEGF) or Cox-2, and immunosuppressive lymphokines such as IL-10, the tumor-associated macrophages promote further development of an immunosuppressive environment." (PMID 36173644, 2022). "Associated with this description, IL-10 has been described with antitumor activity in the tumor microenvironment and with neovascularization inhibitory activity in a murine model, fulfilling a role in the suppression of tumor growth." (PMID 36296636, 2022). "Particularly, DC-SIGN engagement in the tumour microenvironment by fucose-based pathogen-associated molecular patterns (PAMPs) enhances interleukin -10 and -27 (IL-10, IL-27), as well as Th2-attracting chemokine expression, shifting Thelper polarization from Th1 to Th2." (PMID 35428302, 2022). "The tumor milieu is dominated by tumor-associated macrophages, which may release IL-10 and growth factors that promote tumor development, aggression, and metastasis as one of the most essential elements." (PMID 35093033, 2022). "The increased expression of IL-10 was unexpected since IL-10 usually works as an anti-inflammatory and pro-oncogenic agent because it is associated with regulatory T lymphocytes and the M2 polarization of tumor-associated macrophages." (PMID 36500861, 2022). "In a preclinical model of lung cancer, it was demonstrated that MDSC-associated IDO modulates the in vivo and ex vivo differentiation of B regulatory cells (Bregs), an IL-10 producing subset of B cells, found to be reduced in tumor-bearing IDO deficient mice (IDO-/-)." (PMID 35874749, 2022). "Furthermore, we found a significant association between EVs bearing PD-L1 and plasma levels of IL-10 at baseline for subjects with DLBCL tumor subtype (n = 32, Spearman’s ρ = 0.47, p = 0.007)." (PMID 35655072, 2022). "The activation of STAT3 helps tumor cells to evade NK cell-mediated immune surveillance, which is associated with high expression of tumor-promoting cytokines and growth factors, such as IL-10, TGF-β, and vascular endothelial growth factor-A." (PMID 36601109, 2022). "Th2 cell was proposed to promote tumor progression through the secretion of cytokines interleukin (IL)‐4, IL‐6, IL‐10, and IL‐13 to activate tumor‐associated M2 macrophages, and which was found to be a risk factor of male patients in SARC, LUAD, KIRP, PAAD, KIRC, and LIHC (HR > 1, Wald P < 0.05)." (PMID 35229456, 2022). "In a multi-variant analysis, IL-10 was associated with poor outcomes indicating that tumor IL-10 may drive immune escape." (PMID 35255925, 2022).
tumor (continued). "In addition to cell-cell contact, tumor cells can release plenty of molecules with associated receptors on macrophages, such as CSF-1, Chemokines, and IL-10, resulting in the reprogramming of macrophages." (PMID 36497444, 2022). "By flow cytometric analysis we showed that tumors in IP6K1 KO mice contain high levels of CD11b+Gr1 + IL10+ myeloid cells (e.g., neutrophils, monocytes) and lower infiltration of M1-polarized tumor-associated macrophage (TAM), dendritic cells, and CD8+ killer T cells into tumors." (PMID 35308129, 2022). "The presence of immuno-suppressive cytokines (TGF-β, IL-10), chemokines, and regulatory immune-suppressive cells, such as tumor-associated macrophages/microglia (GAMs) and myeloid-derived suppressor cells (MDSCs), limits the effectiveness of current therapies and are briefly review below." (PMID 35603195, 2022). "Moreover, AOM/DSS tumor associated macrophages uniquely express Il10 and Tnf, implicating heightened tumor-promoting immunosuppression and inflammation." (PMID 35600339, 2022). "It is important to note that DLBCL tumor subtype had overall reduced plasma levels of PD-L1+ EVs compared to the Burkitt’s NHL subgroup, raising the possibility that the positive and significant association between PD-L1+ EVs and plasma levels of IL-10 is due to tumor type." (PMID 35655072, 2022). "M2 macrophages can be further classified into different subtypes, namely M2a (mediated by IL4 and IL13), M2b (mediated by immune complexes (IC) with LPS or IL1R ligand), M2c (mediated by TGFB1, IL10, and glucocorticoids), and M2d (activated by tumor-associated factors, the major part of TAMs)." (PMID 36211379, 2022). "Tumor-associated macrophages (TAMs) secrete immunosuppressive cytokines (IL-10 and TGF-β)." (PMID 34654437, 2021). "On the other hand, hypoxia induced release of chemoattractants (such as HIF-1α and HIF-2α) and tumor derived cytokines (such as IL-10, IL-4, and TGF-β) are able to hijack tumor-associated macrophages (TAMs) and tumor-associated dendritic cells (TADCs) functions, resulting in tumor metastasis." (PMID 33761933, 2021). "Conversely, tumor development was enhanced in IL-10-deficient mice." (PMID 33578830, 2021). "CD4 T lymphocytes evolving in a tumor environment rich in IL-2 (in association with TGFβ) express the transcription factor Foxp3, which impairs the differentiation of Tregs and the production of IL-10, that participate in an immunosuppressive microenvironment." (PMID 33498483, 2021). "TME consists of immune cells, including myeloid-derived suppressor cells (MDSCs), Tregs, and tumor-associated macrophages (TAMs), and molecular factors, including checkpoint inhibitory proteins, IL-10, and TGF-β, that inhibit anti-tumor functions of CAR-T cells." (PMID 33522929, 2021). "Tumor-associated macrophages (TAMs) expressing M2 (alternatively activated)-like phenotype imitate type II T-helper cells that express interleukin (IL)-4, IL-5, IL-6, IL-13, and IL-10 to suppress anti-tumor immune response." (PMID 34831357, 2021). "Apoptotic cell clearance via efferocytosis polarizes tumor-associated macrophages (TAM) to adopt pro-tumor ‘M2’ wound-healing phenotypes which, by secreting cytokines such as IL-4, IL-10, IL-13 and TGF-β1, further educate Th0 or Th1 CD4 T cells towards a Th2 phenotype." (PMID 34359823, 2021). "Exosomes isolated from tumor cell supernatants or cancer patients show a rich expression of Fas ligand (FasL), PD-L1, IL-10, TGF-β, tumor-associated antigens, and ectoenzymes engaged in the adenosine pathway (CD39 and CD73), which all contribute to immunoevasion." (PMID 34948368, 2021). "Furthermore, the amount of MDSC was linked to serum concentrations of IL-10 (that has immunosuppressive activity) and to tumor progression and poor prognosis." (PMID 33430142, 2021). "In addition, PD-L1-expressing HLA-DR+ macrophages were associated with poor survival and PD-L1-expressing IgA+IL-10+ B cells suppress anti-tumor CD8+ T cell responses." (PMID 34575463, 2021).